EPO (erythropoietin)
Diseases named in the same sentence as EPO in open-access papers (continued):
Sharing a sentence is not in itself a finding about the gene and the disease.
pseudoexfoliation glaucoma (2 papers, 2012 to 2023). "The aqueous EPO level is proportionate to the level of IOP in eyes with pseudoexfoliation glaucoma." (PMID 36769310, 2023).
renal osteodystrophy (2 papers, 2010 to 2025). Abnormalities of bone mineral metabolism associated with chronic kidney disease. "This lack of response termed “Erythropoietin Resistance” or “Erythropoietin Hyporesponsiveness” is multifactorial but may be related to iron stores (both absolute and effective), renal osteodystrophy, and inflammation." (PMID 20169072, 2010).
retinal (2 papers, 2014 to 2018). "In this study we analyze if EPO or EPO-like peptide can safeguard the neuroglialvascular unit in a model of retinal neurodegeneration and secondary vasoregression." (PMID 25013951, 2014).
sarcoma (2 papers, 2004 to 2023). A usually aggressive malignant neoplasm of the soft tissue or bone. "However, for the tumour line used in the present study (DS-sarcomas of the rat), it has been shown that EPO per se has no promoting effect on proliferation." (PMID 15305198, 2004).
spinal cord ischemia (2 papers, 2014 to 2022). Reduced blood flow to the spinal cord which is supplied by the anterior spinal artery and the paired posterior spinal arteries. "It was shown in animal models, that EPO and cEPO may attenuate damage after spinal cord ischemia (SCI)." (PMID 36076955, 2022).
thromboses (2 papers, 2006 to 2018). "Combining the results of a recent publication and our own experience, we note 6 cases of grade 4 or 5 TE in patients receiving cisplatin and concurrent irradiation without erythropoietin for malignant disease including two deaths from thromboses." (PMID 16722547, 2006).
ventricular fibrillation (2 papers, 2016). A disorder characterized by an electrocardiographic finding of a rapid grossly irregular ventricular rhythm with marked variability in QRS cycle length, morphology, and amplitude. "In animals exposed to ventricular fibrillation, EPO treatment has protective effects on the adrenal gland." (PMID 27504455, 2016). "After the end of an 8-minute ventricular fibrillation, the control group (Group C) received saline as placebo, whereas the EPO group (Group E) received EPO 5000 U/kg." (PMID 27847811, 2016). "Ventricular fibrillation was induced via pacing wire forwarded into the right ventricle in 20 female Landrace/Large White pigs, allocated into 2 groups: experimental group treated with bolus dose of erythropoietin (EPO) and control group which received normal saline." (PMID 27504455, 2016). "As it has been hypothesized that EPO might have a multiorgan protection role, the present study aimed at better understanding of the pathophysiology of adrenal insufficiency and the possible protective effects of EPO at adrenal level, in an experimental animal model of ventricular fibrillation (VF)." (PMID 27504455, 2016).
vitamin A deficiency (2 papers, 2006 to 2025). Deficiency of vitamin A due to malnutrition, malabsorption, or dietary lack. "For example, previous literature has established that vitamin A is involved in iron homeostasis and vitamin A deficiency reduces renal erythropoietin thereby inhibiting erythropoiesis." (PMID 41459083, 2025). "Thus, it is possible that vitamin A deficiency might have reduced the EPO response to low hemoglobin concentrations." (PMID 16390553, 2006).
vitamin B deficiency (2 papers, 2021 to 2023). A condition due to deficiency in any member of the vitamin B complex. "Impaired response of the bone marrow to EPO may occur as a consequence of the action of circulating uremic toxins, inflammation, vitamin B deficiency, and/or decreased availability of iron for erythropoiesis." (PMID 34209294, 2021).
vitreous hemorrhage (2 papers, 2016 to 2017). Blood extravasation in the vitreous humor. "Elevation of EPO, VEGF and vitreous hemorrhage began on approximately P4; and by 3 weeks of age, these mice typically progressed to tractional retinal detachment." (PMID 27195131, 2016).
α‐thalassemia (2 papers, 2022). "Additionally, we show that α‐thalassemia not only increases hemoglobin in patients with HbSS (p = .0009) but also reduces erythropoietin values (p = .0005), demonstrating a measurable response to improved tissue oxygenation." (PMID 35802781, 2022). "Reflecting on the changes seen with Hb, we found EPO values were lower in individuals with HbSS and co‐inherited α‐thalassemia, but not in patients with HbSC and co‐inherited α‐thalassemia." (PMID 35802781, 2022).
acute leukemia (1 paper, 2021). A clonal (malignant) hematopoietic disorder with an acute onset, affecting the bone marrow and the peripheral blood. "The median EPO concentration was the highest in untreated patients with acute leukemia (group II) (p = 0.004 in comparison to group III, and p < 0.001 in comparison to other groups)." (PMID 34204310, 2021).
acute-on-chronic liver failure (1 paper, 2021). Acute-on-chronic liver failure (ACLF) is an extreme condition during the natural history of chronic HBV infection, with a relatively high short-term mortality. "Erythropoietin (EPO) was a biomarker of predicting prognosis in patients with Acute-on-chronic liver failure (ACLF), and patients without bleeding showed a lower level of EPO59." (PMID 34021184, 2021).
alcoholic fatty liver disease (1 paper, 2019). Lipid infiltration of the hepatic parenchymal cells that is due to alcohol abuse. "In addition to EPO regulation of fat mass accumulation in white adipose tissue, EPO decreased lipid accumulation in the liver while stimulating STAT3/STAT5 activation and promoting lipolysis in white adipose tissue, suggesting benefit in non-alcoholic fatty liver disease." (PMID 32038269, 2019).
angiomyolipoma (1 paper, 2009). A neoplasm with perivascular epithelioid cell differentiation often associated with tuberous sclerosis. "Western blot analysis showed relatively decreased EPO and EPO-R levels in the angiomyolipoma." (PMID 19946506, 2009). "In this patient, we also provided EPO and EPO-R evaluation, which showed a reduction in levels that proved that the angiomyolipoma was not a direct source of erythrocytosis." (PMID 19946506, 2009).
anterior uveitis (1 paper, 2015). Inflammation of the iris and anterior chamber of the eye. "Although not well established, an association between epoetin alfa, a human recombinant erythropoietin, and anterior uveitis has been reported previously in the literature, with 13 patients across three medical centers developing anterior uveitis after receiving epoetin alfa during hemodialysis." (PMID 26502332, 2015).
aortic aneurysm (1 paper, 2022). A ruptured aneurysm located in the wall of the proximal portion of the descending aorta proceeding from the arch of the aorta. "Our results are in line with a recent study showing that EPO repetitive injection promoted aortic aneurysm in Apoe−/− mice." (PMID 36329047, 2022). "EPO treatment promoted aortic dilation after 4 weeks and 7 weeks, as well as aortic aneurysm (0 vs 58 %, P < 0.05) and lethal rupture (0 vs 42%, P < 0.05)." (PMID 36329047, 2022). "We also found that high doses of EPO induced dissecting aortic aneurysm in immunocompetent C57BL/6 mice, supporting the critical role of the JAK2 pathway in aortic disease, but we did not specifically investigated which cell type was activated in response to EPO supplementation." (PMID 36329047, 2022).
aortic stenosis (1 paper, 2020). Aortic valve stenosis is a aortic valve disease caused by the incomplete opening of the aortic valve. "EPO levels add to the existing prognostic biomarkers in patients with severe aortic stenosis in the TAVR era." (PMID 33330669, 2020). "High EPO levels could be useful to identify patients with severe aortic stenosis showing a compromised mid-term survival in spite of TAVR use and independently from early TAVR results." (PMID 33330669, 2020). "Thus, it could be worth to specifically investigate the impact of endogenous baseline EPO levels in patients with a low-flow low-gradient aortic stenosis, since this population can be characterized by a reduced cardiac output." (PMID 33330669, 2020). "The EPICURE randomized clinical trial, an intervention study of exogenous EPO use, has shown negative results also in patients with severe aortic stenosis." (PMID 33330669, 2020).
astrocytoma (1 paper, 2022). "The genes CDH2, DDB2, DSP, EPO, FGF2, and TEK were overexpressed in an astrocytoma cell line." (PMID 36142793, 2022).
autoimmune optic neuritis (1 paper, 2022). An autoimmune form of optic neuritis. "Since EPO has shown multiple neurotrophin-like properties in various neuronal disorders, the efficacy of EPO is evaluated as an add-on therapy to methylprednisolone in autoimmune optic neuritis by investigators." (PMID 35806148, 2022).
bacterial meningitis (1 paper, 2014). Inflammation of the membranes surrounding the brain and spinal cord due to a bacterial infection. "EPO treatment has also shown long-term efficacy in improving cognitive outcomes in rats with bacterial meningitis, but no studies have investigated the efficacy of EPO treatment in a dual injury model." (PMID 25082427, 2014).
Balkan nephropathy (1 paper, 2020). A chronic tubulointerstitial nephropathy that affects people in certain rural areas along the Danube river in the Balkans. "Our group observed that erythropoietin (EPO), a kidney produced hormone, prevents TH17 induction and ameliorates renal injury in a murine model of Balkan nephropathy." (PMID 32765535, 2020).
behavioral abnormalities (1 paper, 2024). "In parallel, another unexpected observation from a recent study was an increased incidence of behavioral abnormalities in two-year-old children who had been treated with erythropoietin compared with those who received a placebo." (PMID 38804373, 2024).
blood pressure (1 paper, 2015). "In these patients multiple factors can cause high blood pressure including fluid overload, activation of rennin angiotensin-aldosterone axis or use of exogenous erythropoietin that make it difficult to evaluate the causative mechanism." (PMID 26312236, 2015).
bone marrow failure syndrome (1 paper, 2024). "Given the frequency of BM failure within the pedigree, we examined known recurrent mutations of inherited bone marrow failure syndromes, such as mutations in genes encoding ribosomal proteins (RP), ALAS2, GATA1, CDAN1, EPO, EPOR, etc.." (PMID 38971858, 2024).
Budd-Chiari syndrome (1 paper, 2022). "There are a few published case reports of elevated EPO levels associated with PV and Budd-Chiari syndrome (BCS)." (PMID 35800822, 2022).
cavernous hemangioma (1 paper, 2016). A hemangioma characterized by the presence of cavernous vascular spaces. "Previous studies found that the signal pathway involving the von Hippel-Lindau (VHL) factor, the HIF-2α transcriptional factor, and HIF-2α target gene erythropoietin (EPO) could affect the formation of cavernous hemangiomas in mouse livers." (PMID 27872856, 2016).
celiac disease (1 paper, 2013). An autoimmune genetic disorder with an unknown pattern of inheritance that primarily affects the digestive tract. "Decreased purine synthesis results in impaired DNA synthesis, which then leads to megaloblastic anemia, due to slowed renewal of RBC's from multipotent progenitors, a problem that is compounded by suppressed EPO activity, a feature of celiac disease." (PMID 24678255, 2013). "Low EPO levels, leading to a low turnover rate of red blood cells, is a feature of celiac disease." (PMID 24678255, 2013).
cerebral lesions (1 paper, 2026). "The goal of the current investigation is to assess whether erythropoietin administration influenced inflammatory optic nerve and cerebral lesions or optic nerve atrophy on MRI." (PMID 42004010, 2026).
cervical squamous cell carcinoma (1 paper, 2019). A squamous cell carcinoma arising from the cervical epithelium. "Erythropoietin (EPO) and erythropoietin receptor (EPO-R) could produce an angiogenic effect to promote cervical squamous cell carcinoma (CSCC) progression." (PMID 30915348, 2019).
choroidal (1 paper, 2018). "We hypothesized that systemic EPO facilitates the development of choroidal neovascularization (CNV)." (PMID 29391474, 2018).
chronic skin ulcers (1 paper, 2014). "Clinical studies have already shown that systemic or topic EPO treatments had beneficial therapeutic effects on wound healing of chronic skin ulcers." (PMID 25422898, 2014).
Chylothorax (1 paper, 2022). The presence of chyle in the thoracic cavity. "Increased GM-CSF and EPO and decreased VEGF indeed may have contributed to the higher incidence of chylothorax and longer inotropic support in the DS/CHD population." (PMID 35352006, 2022).
CO poisoning (1 paper, 2012). "All together, it seems that measuring these brain injury biomarkers could be valuable in prognosis of CO poisoning and also to monitor potential therapies (like EPO) in CO poisoning." (PMID 23493953, 2012).
coronary artery stenosis (1 paper, 2022). "The ischemia and hypoxia developed in the myocardial tissue when coronary artery stenosis is present activates RASS system and increases the angiotensin II level, motivates the secretion of erythropoietin, and consequently irritates erythropoiesis." (PMID 35722627, 2022).
craniosynostosis (1 paper, 2022). Craniosynostosis is defined as the premature fusion of one or more cranial sutures leading to secondary distortion of skull shape resulting in skull deformities with a variable presentation. "As the literature involving EACA use in craniosynostosis is limited, further studies investigating its optimal dosing, interactions with erythropoietin, as well as other effects are necessary to elucidate the true applications of this therapeutic agent." (PMID 35747005, 2022).
Cyanosis (1 paper, 2024). Bluish discoloration of the skin and mucosa due to poor circulation or inadequate oxygenation of arterial or capillary blood. "However, cyanosis causes (patho-) physiological adaptations to improve oxygen transport and delivery to the tissues, including increased erythropoietin stimulus leading to secondary erythrocytosis which results in elevated HCT and reduced plasma volume." (PMID 39713224, 2024).
delirium (1 paper, 2024). A disorder characterized by confusion; inattentiveness; disorientation; illusions; hallucinations; agitation; and in some instances autonomic nervous system overactivity. "This study aimed to determine the role of perioperative EPO administration in the development of postoperative delirium in older adult patients undergoing total joint arthroplasty." (PMID 39548414, 2024). "This study aimed to assess the impact of perioperative EPO administration on the incidence of postoperative delirium and further investigate its effects on post-operative cognitive function and inflammatory response in older patients undergoing total joint arthroplasty." (PMID 39548414, 2024). "In conclusion, EPO reduced both the incidence of post-operative delirium and the degree of decline of MMSE scores, although not statistically significant." (PMID 39548414, 2024). "Based on our results, EPO reduced the incidence of postoperative delirium, although it was not statistically significant." (PMID 39548414, 2024). "None of the patients in the EPO group experienced delirium, whereas one patient in the control group developed delirium (0 vs. 3.2%, P = 0.500)." (PMID 39548414, 2024). "One patient in the control group developed delirium on POD 2 (3.2%), whereas no patient in the EPO group developed PD (0% vs. 3.2%, p = 0.500)." (PMID 39548414, 2024).
developmental disabilities (1 paper, 2021). "The capability of EPO to increase, on the one hand, the number of immature PV+ cells and to stimulate, on the other hand, the maturation of PV-basket cells makes this paradigm relevant for therapeutic applications in the treatment of developmental disabilities." (PMID 33495244, 2021).
diabetic eye disease (1 paper, 2019). A group of disorders affecting the eye in patients with diabetes mellitus. "A statistically significant worsening of DR in the group of patients using rhEPO compared to the non-receiving group was also noted, and a direct proportionality of the serum erythropoietin concentration and the deterioration of diabetic eye disease was determined." (PMID 31727007, 2019).
dysplasia (1 paper, 2007). A usually neoplastic transformation of the cell, associated with altered architectural tissue patterns. "Our aim was to assess the immunohistochemical expression of hypoxia-inducible factor (HIF)-1α, HIF-2α, erythropoietin (Epo), Epo receptor (Epo-R), Glut-1 and vascular endothelial growth factor (VEGF) along with Ki67/MIB-1 in the Barrett's metaplasia–dysplasia–adenocarcinoma sequence." (PMID 17437013, 2007).
E. coli infections (1 paper, 2021). "Given that E. coli infections are an important worldwide health concern, we investigated the role of EPO in an E. coli-initiated infection resolution." (PMID 33927725, 2021).
embryonal carcinoma (1 paper, 2012). A non-seminomatous malignant germ cell tumor characterized by the presence of large germ cells with abundant cytoplasm resembling epithelial cells, geographic necrosis, high mitotic activity, and pseudoglandular and pseudopapillary structures formation. "Tretinoin (retinoic acid) stimulated erythropoietin gene transcription in embryonal carcinoma cells through the direct repeat of a steroid/thyroid hormone receptor response element half-site in the hypoxia-response enhancer element." (PMID 23282076, 2012).
endometrial disorder (1 paper, 2019). A non-neoplastic or neoplastic disorder that affects the endometrium. "However, the role of EPO in endometrial disorders is still unknown." (PMID 29916217, 2019).
Fabry disease (1 paper, 2018). Fabry disease (FD) is a progressive, inherited, multisystemic lysosomal storage disease characterized by specific neurological, cutaneous, renal, cardiovascular, cochleo-vestibular and cerebrovascular manifestations. "As model RPs, we used an α‐Galactosidase (αGal) used to treat Fabry's disease, the hematopoietic glycohormone erythropoietin (EPO) and the HIV‐neutralizing antibody VRC01." (PMID 29509983, 2018).
familial erythrocytosis type 3 (1 paper, 2008). "Deficiency of this gene causes familial erythrocytosis type 3 (ECYT3) (MIM# 609820), which is characterized by increased serum hemoglobin and hematocrit levels, but normal serum erythropoietin levels." (PMID 19108714, 2008).
gastric tumors (1 paper, 2024). "Notably, the transcriptional features of EPO-GEMM tumors correlated with those of human gastric tumors of the respective subtypes, which was largely driven by dominant MYC, proliferation and immune-related signatures." (PMID 38177458, 2024).
Gaucher disease (1 paper, 2007). Gaucher disease (GD) is a lysosomal storage disorder encompassing three main forms (types 1, 2 and 3), a fetal form and a variant with cardiac involvement (Gaucher disease - ophthalmoplegia - cardiovascular calcification or Gaucher-like disease). "EPO has also been associated with a risk of thrombosis and, in combination with evidence of increased blood cell aggregation in Gaucher disease, may incur unacceptable risks." (PMID 17655728, 2007).
generalized anxiety disorder (1 paper, 2024). An anxiety disorder characterized by excessive and difficult-to-control worry about a number of life situations. "The diagnostic usefulness of EPO levels has been investigated in children with ADHD and adults with generalized anxiety disorder (GAD)." (PMID 38995319, 2024).
glomerulosclerosis (1 paper, 2013). A hardening of the kidney glomerulus caused by scarring of the blood vessels. "Recent study in rats with kidney transplantation and EPO treatment prevented chronic allograft dysfunction by ameliorated glomerulosclerosis, TA/IF, and inflammatory cell infiltration and preserved graft function." (PMID 24350257, 2013).